SSB (small RNA binding exonuclease protection factor La)
Description:
Binds to the 3' poly(U) terminus of nascent RNA polymerase III transcripts, protecting them from exonuclease digestion and facilitating their folding and maturation. In case of Coxsackievirus B3 infection, binds to the viral internal ribosome entry site (IRES) and stimulates the IRES-mediated translation.
Synonyms: SSB/La; LARP3; La; La/SSB
Tractability: Small molecule: it has a binding pocket of medium quality. PROTAC: ubiquitination databases record sites on it; its protein half-life has been measured.
Gene: Protein-coding gene on chromosome 2 (169,791,933 to 169,812,091, forward strand). Ensembl gene ENSG00000138385.
Subcellular location: Nucleus
Subcellular location (Human Protein Atlas): Nucleoplasm
Pathways (Reactome):
Gene expression (Transcription): RNA Polymerase III Abortive And Retractive Initiation; RNA Polymerase III Transcription Termination
Gene Ontology:
Molecular function: poly(U) RNA binding; protein binding; RNA binding; sequence-specific mRNA binding; tRNA binding; mRNA binding; nucleic acid binding
Biological process: IRES-dependent viral translational initiation; nuclear histone mRNA catabolic process; protein localization to cytoplasmic stress granule; tRNA 3'-end processing; tRNA 5'-leader removal; tRNA export from nucleus; tRNA processing; histone mRNA metabolic process; positive regulation of translation; tRNA modification; RNA processing
Cellular component: chromosome, telomeric region; cytoplasm; nucleus; cytoplasmic stress granule; cytosol; ribonucleoprotein complex
Genetic constraint (gnomAD): Loss-of-function variants: 11 observed, 44.91 expected, observed/expected ratio (o/e) 0.24, 90% interval 0.15 to 0.41. The synonymous counts are far from expectation, so gnomAD's model fits this gene poorly and the ratio says little. Missense variants: 291 observed, 451.68 expected, observed/expected ratio (o/e) 0.64, 90% interval 0.58 to 0.71. Synonymous variants: 105 observed, 152.08 expected, observed/expected ratio (o/e) 0.69, 90% interval 0.59 to 0.81.
Homologues: Orthologues: chimpanzee SSB (100% identical), guinea pig SSB (96% identical), rabbit SSB (95% identical), dog SSB (94% identical), rat Ssb (80% identical), mouse Ssb (80% identical), rat AABR07061825.1 (78% identical), pig SSB (76% identical), tropical clawed frog ssb (62% identical), zebrafish ssb (56% identical), Caenorhabditis elegans ssb-1 (32% identical), Drosophila melanogaster La (30% identical). Paralogues in human: LARP7 (24% identical), LARP6 (16% identical), LARP1 (15% identical), LARP1B (15% identical), LARP4 (14% identical), LARP4B (14% identical).
Diseases named in the same sentence as SSB in open-access papers:
SSB is named in the same sentence as 164 diseases in open-access papers, as found by Europe PMC text mining. Sharing a sentence is not in itself a finding about the gene and the disease. The quoted sentences say what the papers report.
Sjögren’s syndrome (125 papers, 2006 to 2026). "The production of anti-SSB antibodies is a hallmark of Sjögren’s syndrome, but can also be found in systemic lupus erythematosus and RA patients." (PMID 32486012, 2020). "For example, autoantibodies anti-Ro-SSA or anti-La-SSB, which are markers of Sjögren’s syndrome, have been shown to be associated with higher IMT scores and lower ABI and NMV16,18,29." (PMID 29396489, 2018). "However, it is interesting to note that anti-SSA and anti-SSB autoAbs are associated with primary Sjögren’s syndrome where frequent development of anti-IFN-I autoAbs has been reported." (PMID 39017930, 2024). "Finally, even though antibodies to SSB are a hallmark of Sjögren’s syndrome, these antibodies are also found in RA." (PMID 27729089, 2016). "Anti-SSA and anti-SSB antibody are frequently found in SLE patients with the positivity ranged from 34% to 83% in different reports and higher prevalence of anti-SSA/SSB antibody could be observed in SLE patients associated with secondary Sjogren's syndrome." (PMID 24864270, 2014). "BCMA-CAR-T cells effectively reduce autoantibodies (e.g., anti-SSA/SSB in Sjögren’s syndrome) but induce hypogammaglobulinemia, which is manageable via intravenous immunoglobulin (IVIG) supplementation." (PMID 41200159, 2025). "A population-based Swedish study demonstrated that the increased MM risk in Sjögren’s syndrome patients was restricted to those positive for SSA and SSB autoantibodies." (PMID 40061899, 2025). "Serological studies showed positive anti-SSA (Sjögren's-syndrome-related antigen A) (Ro) and anti-SSB (Sjögren's-syndrome-related antigen B) (La) antibodies, consistent with her established diagnosis of Sjögren's syndrome." (PMID 40385803, 2025). "Serological testing demonstrated positive antinuclear and anti-SSb/La antibodies, consistent with Sjögren’s syndrome as an immune-related adverse event (irAE)." (PMID 40361988, 2025). "Following stabilization, further evaluation revealed positive antinuclear antibody (ANA) and anti-Ro/SSA, anti-La/SSB, and Ro52 antibodies, confirming Sjögren's syndrome." (PMID 41404221, 2025). "Sjögren’s syndrome (SS) is typically diagnosed late making it challenging to identify correlations between specific antibodies like SSA/SSB and gut microbiota alterations." (PMID 38898418, 2024). "The prevalence of anti-SSA and anti-SSB antibodies was higher in SLE patients with secondary Sjogren’s syndrome." (PMID 37344560, 2023). "For example, anti-SSA and anti-SSB in Sjögren’s syndrome, and cryoglobulins have been repeatedly found in patients with chronic hepatitis B, C, and E infection." (PMID 37387781, 2023). "Meanwhile, anti-Ro/SSA and anti-La/SSB antibodies are present in approximately 30% and 20% of SLE patients, respectively, but they are generally more strongly associated with Sjogren’s syndrome." (PMID 36325322, 2022). "Mononuclear cell infiltration of exocrine glands, production of Ro/SSA and La/SSB autoantibodies, along with oral and ocular dryness, are characteristic features of primary Sjögren’s syndrome (pSS)." (PMID 31366407, 2019). "Hypergammaglobulinemia is closely associated with the key immunological markers of Sjögren’s syndrome (rheumatoid factor, anti-Ro/SSA, and anti-La/SSB)." (PMID 28783737, 2017). "Anti-SSA/Ro60 and anti-SSB/La are essential serological biomarkers for rheumatic diseases, specifically Sjögren’s syndrome (SS) and systemic lupus erythematosus (SLE)." (PMID 27184054, 2016). "A diagnosis of Sjogren’s Syndrome requires either positive SSA/SSB or positive minor salivary gland biopsy, and an additional 3 out of 6 diagnostic criteria." (PMID 23776474, 2013). "The proteins Ro60 (TROVE2, SSA) and La (SSB), which are common auto-antigens in autoimmune diseases (like systemic lupus erythematosus and Sjögren’s syndrome, were identified as the major antigens facilitating the association with these small ncRNAs." (PMID 24970161, 2013).
Sjögren’s syndrome (continued). "Schirmer's test, tear breakup time, antinuclear antibodies (ANA) by immunofluorescent assay, ANA blot demonstrating the presence of anti-SSA (Ro) and/or anti-SSB (La) antibodies, and lip biopsy were conducted in all cases, which confirmed the diagnosis of Sjogren's syndrome." (PMID 39552968, 2024). "It develops in fetuses of women with anti-Ro/SSA and anti-La/SSB autoantibodies who may have autoimmune diseases, such as Sjögren’s syndrome (SS) and systemic lupus erythematosus (SLE); however, it may not be associated with other diseases." (PMID 38167489, 2024). "Moreover, some authors have found that anti-SSA or anti-SSB antibodies can be present at a high percentage in the early phase of Sjögren’s syndrome, even years before the clinically manifested disease, or in seemingly healthy people." (PMID 37256208, 2023). "The RF-IgM/SSA/SSB subgroup share features with Sjögren's syndrome." (PMID 31156624, 2019). "Anti-SSB antibodies are particularly frequent in Sjögren's syndrome." (PMID 30363993, 2018). "The earliest ANAs are anti-Ro/Sicca Syndrome (SS)-A and anti-La/SSB Abs, on average 3.7 years before, followed by anti-dsDNA Abs, on average 2.2 years before, and the anti-Smith (Sm) ribonucleoprotein (RNP) Abs, on average 0.9 years before the advent of clinical symptoms." (PMID 22162716, 2012). "Anti-sicca syndrome (SS)A and anti-SSB Abs were then tested in these 161 subjects." (PMID 18782791, 2009). "It has also been demonstrated that autoimmune sera from patients with primary Sjögren’s syndrome and SLE contain anti-Id Abs, anti-La/SSB antibodies, which inhibit the binding of anti-La/SSB antibodies to recombinant La/SSB by 91%." (PMID 41441690, 2025). "LIP is usually associated with connective tissue disorders (such as systemic lupus erythematosus and Sjogren syndrome) and HIV; hence, serological testing (SSA, SSB, HIV antibody) is warranted." (PMID 37435256, 2023). "The characteristic antibodies of Sjögren’s syndrome, anti-SSA and anti-SSB, are found in 24–60% of patients with SLE, and are associated with neonatal SLE." (PMID 37047548, 2023). "Elevated autoantibodies consistent with pre‐existing Sjogren's syndrome were also found (anti‐SSA/Ro antibodies 5990 U/mL and anti‐SSB/La antibodies 2320 U/mL)." (PMID 37082169, 2023). "Some assays of ANA-ELISA have resolved this issue by adding a number of extra purified recombinant antigens, as is the case of some of the classical epitopes of Sjogren’s syndrome (Ro/SSA and La/SSB) and also in other rheumatic autoimmune diseases." (PMID 36325321, 2022). "In Sjögren’s syndrome, an autoimmune disease defined by sicca symptoms of oral and ocular dryness, the major autoantibodies are against SSA and SSB." (PMID 33763057, 2021). "TLS within inflamed synovium or salivary glands in patients with rheumatoid arthritis or Sjögren’s syndrome, control the production of anti-citrullinated peptide antibody, anti-Ro/SSA and anti-La/SSB antibodies." (PMID 34335608, 2021). "Sjögren’s syndrome (pSS), defined as presence of xerostomia, xerophthalmia, anti-SSA or anti-SSB antibodies and typical salivary gland histology is rare in patients with HCV infection." (PMID 34835054, 2021). "To test the generalizability of the method in an additional autoimmune disease, we identified and validated autoantigenic signals to SSB, CENPA, and keratin proteins in a cohort of individuals with Sjogren’s syndrome (n=91)." (PMID 33986742, 2021). "In this control cohort, 79 patients (10%) carried a diagnosis of secondary Sjögren’s syndrome, 148 (19%) had anti-Ro/SSA antibodies, and 51 (7%) had anti-LA/SSB antibodies." (PMID 32644976, 2020). "The diagnosis of amyloidosis followed the onset of the Sjögren syndrome by 1 to 25 years, and hypergammaglobulinemia, positive RF and/or anti-SSA and anti-SSB antibodies were observed in the majority of patients." (PMID 33120855, 2020).
Sjögren’s syndrome (continued). "In the salivary gland ELSs of patients with Sjögren syndrome, B cells and plasma cells are frequently reactive against the ribonucleoproteins Ro/SSA and La/SSB, whereas autoantibodies specific for RA are RF and ACPA." (PMID 31275325, 2019). "Repeated injection of recombinant OmpA reproduced mononuclear cell inflammation of the Harderian and salivary glands in mice and elevation of autoantibodies against Sjögren’s-syndrome-related antigens SSA/Ro and SSB/La." (PMID 30347705, 2018). "Sjögren’s syndrome-specific autoantibodies, anti-SSA and anti-SSB, are detectable in 12–16-week-old TSP1−/− mice." (PMID 30314337, 2018). "The typical autoantibodies in primary Sjögren’s syndrome are anti-SSA/Ro and anti-SSB/La antibodies, which are routinely identified as part of extractable nuclear antigen (ENA) laboratory screening." (PMID 30585183, 2018). "More studies are warranted to effectively diagnose Sjogren syndrome, as positive serum anti-SSA/Ro and/or anti-SSB/La, and keratoconjunctivitis sicca." (PMID 29250546, 2017). "Key words:Primary Sjögren’s syndrome, salivary diagnostics, anti-SSA autoantibodies, anti-SSB autoantibodies." (PMID 25475778, 2015). "Sjögren's syndrome is further characterized by several autoantibodies - such as anti-SSA (anti-Ro), anti-SSB (anti-La) and rheumatoid factor - and B-cell hyperactivity." (PMID 23566679, 2013). "These sicca-like symptoms prompted a workup for Sjögren's syndrome but antinuclear antibodies, anti-SSA/anti-SSB antibodies and minor salivary gland biopsies all were negative." (PMID 21914217, 2011). "Seronegative sicca syndrome encompasses patients who present with xerostomia and/or keratoconjunctivitis sicca but lack anti-SSA/SSB antibodies and do not fulfill current classification criteria for primary Sjögren’s syndrome (pSS)." (PMID 40566617, 2025). "The aim of this study was the assessment of the relationship between endothelial dysfunction and serum cytokines, anti-SSA and anti-SSB antibodies, beta-2 microglobulin levels, focus score, and EULAR Sjögren’s Syndrome Disease Activity Index (ESSDAI) in pSS patients." (PMID 37762225, 2023). "Two studies of Sjögren’s syndrome patients have shown that patients with anti-SSA/SSB antibodies were significantly more likely to develop lymphoma than those without anti-SSA/SSB antibodies." (PMID 37958403, 2023). "To date, only one case of a patient with overt diagnosis of Sjögren’s syndrome with MGMID has been described but a pathogenic role for SSA and SSB antibodies has never been proven." (PMID 37016425, 2023). "In the autoantibodies studies, 59% of the participants had abnormal anti-Ro/SSA and/or anti-La/SSB antibodies, but none fulfilled the criteria for Sjogren’s syndrome." (PMID 28957343, 2017). "The observations suggest that monitoring and prevention of cardiovascular disease in patients with primary Sjögren's syndrome should be considered, and that Ro/SSA and La/SSB autoantibodies may be used as biomarkers to identify the group of patients with the greater need." (PMID 31127862, 2019). "As a result, patients with sicca symptoms who are seronegative for anti-SSA/Ro and anti-SSB/La antibodies—and do not fulfill the ACR/EULAR classification criteria for primary Sjögren’s syndrome—often go unreported in formal registries." (PMID 40566617, 2025). "Previous studies have revealed the presence of anticentromere antibodies in patients with Sjögren’s syndrome (SS), predominantly in those serologically negative for antibodies against Ro/SSA and La/SSB antigens (seronegative)." (PMID 37941855, 2023). "In Sjögren’s syndrome, increases in IgG, anti-SSA, and anti-SSB titers patients’ sera after influenza vaccination without any increase in flare-ups were recently reported." (PMID 31877764, 2019).
Sjögren’s syndrome (continued). "For example, systemic lupus erythematosus and Behcet’s syndrome patients usually have skin and mucosal damage, and Sjogren’s syndrome patients often have symptoms such as dry mouth and dry eyes, with positive serum SSA and SSB antibodies, which are generally not accompanied by organomegaly." (PMID 39969355, 2024). "Importantly, the ACPA response was RA specific since engraftment of ELS+ salivary glands' tissues from patients with Sjögren syndrome leads to the release of anti-Ro/SSA and anti-La/SSB human IgG but not ACPAs." (PMID 36465908, 2022). "Therefore, a sicca syndrome after aHSCT would not be considered an independent primary disease, especially when the typical SSA(Ro) and SSB(LA) antibodies were preexisting before aHSCT." (PMID 34539659, 2021). "Stratifying by autoantibody profile, the hazard ratio of MI after Sjögren's syndrome diagnosis was 1.4 (95% CI 0.8–2.5) in SSA/SSB double‐positive patients, 2.0 (95% CI 1.2–3.4) in SSA/SSB single‐positive patients, and 1.5 (95% CI 0.9–2.5) in SSA/SSB‐negative patients." (PMID 31127862, 2019).
lupus (71 papers, 2006 to 2026). "All patients with the E323G variant were positive for SSA/SSB/dsDNA/nucleosome/histone and other lupus autoantibodies, and two of six had lupus nephritis." (PMID 34889940, 2022). "Immune complex levels of autoantibodies against double-stranded DNA and the SSA/SSB complex show more specific associations with treatment outcome compared with serum levels in belimumab-treated systemic lupus erythematosus patients." (PMID 31783909, 2019). "Maternal immunologic screening demonstrated high titers of anti-SSA/Ro and anti-SSB/La antibodies, leading to the diagnosis of systemic lupus erythematosus." (PMID 41918634, 2026). "The risk is further amplified by factors such as lupus activity, the presence of specific antibodies (like Antiphospholipid antibody (APA), anti-SSA/Ro, and anti-SSB/La), and pre-existing conditions like hypertension." (PMID 38895665, 2024). "Serum expression of SSA and SSB autoantibodies is observed in ~25-75% of SjD patients, respectively, but are also detected in patients with systemic lupus erythematosus and rheumatoid arthritis." (PMID 39936155, 2024). "The lupus‐associated (La) antigen has the HUGO Gene name of Sjögren Syndrome B (SSB) and is also known as La‐related protein 3 (LARP3)." (PMID 34636174, 2022). "We developed and characterized phospho-specific antibodies for DNA ligase 1 (LIG1) pS66 (ARVLGpSEGEEE) and Lupus La protein (SSB) pS366 (KTKFApSDDEHD)." (PMID 35755813, 2022). "In maternal SLE the presence of anti-SSB/La and anti-SSA/Ro antibodies is associated with disorders of the heart conduction system during fetal development and, after birth, in neonatal lupus." (PMID 36148238, 2022). "Anti-Ro/SSA and/or anti-La/SSB are known to contribute to congenital heart block or neonatal lupus development." (PMID 35109877, 2022). "Some genes in the CNV deletion regions were significantly associated with systemic lupus erythematosus, such as tumor necrosis factor (TNF) in chromosome 6 and small RNA binding exonuclease protection factor La (SSB) in chromosome 2." (PMID 34723755, 2021). "Marked IgG and IgM AAb responses against lupus-associated autoantigens including ribonucleoprotein, Smith antigen, DNA, histones, Ro/SSA, SSB, and complement by 1 week PI in BALF and 5 week PI in plasma, peaking at 9 and 13 weeks PI, respectively." (PMID 33732257, 2021). "Hydroxychloroquine is used to prevent fetal heart block and neonatal lupus in women with anti-Ro/SSA or anti-La/SSB antibodies with a previous history of fetal heart block or neonatal lupus." (PMID 34204066, 2021). "Furthermore, infants of mothers with SLE who were exposed to anti-Ro/SSA or anti-La/SSB antibodies during pregnancy have shown an increased risk for neonatal lupus syndrome, with its most serious manifestation being fetal heart block." (PMID 34209187, 2021). "Although anti-Ro/SSA and anti-La/SSB autoantibodies are sometimes found in other autoimmune diseases such as systemic lupus erythematosus, a correlation with a specific differentially expressed gene has not been established." (PMID 32939030, 2020). "Anti-histone antibodies characterize drug-induced lupus, while anti-SSA/Ro and anti-SSB/La antibodies are associated with neonatal lupus erythematosus and photosensitivity." (PMID 24649358, 2014). "A particular category of lupus individuals who had low levels of vitamin D, innate T-cell activation, and nephropathy had elevated levels of circulating sMICA, which were also substantially elevated among those with anti-SSB and anti-RNP autoantibodies." (PMID 38474281, 2024). "These proteins may also be important markers like small RNA binding exonuclease protection factor La (SSB), it is related to systemic lupus erythematosus, which is another common autoimmune disease." (PMID 34925365, 2021).